MALT1 (MALT1 paracaspase)
Diseases named in the same sentence as MALT1 in open-access papers (continued):
Sharing a sentence is not in itself a finding about the gene and the disease.
combined immunodeficiency (8 papers, 2015 to 2025). A broad classification of inherited disorders presenting at birth that affect both the cell-mediated and humoral aspects of the immune response. "The loss of MALT1 contributes to infantile combined immunodeficiency and immune dysregulation coupled with lymphocyte signaling impaired via the NF-κB pathway." (PMID 35309901, 2022). "Of interest, MALT1 deficiency in patients has been associated with combined immunodeficiency, and a case of human MALT1 deficiency in a 15-year-old female was shown to experience significant growth delay with short stature, low weight, and delayed bone age." (PMID 30513612, 2018). "Of note, MALT1 mutation in humans, causing the absence or very low expression of MALT1, leads to combined immunodeficiency (CID), which is characterized by several bacterial, fungal, and viral infections, indicating that targeting MALT1 activity may not be without risk." (PMID 31632405, 2019). "MALT1 deficiency can cause infantile combined immunodeficiency and immune dysregulation without T cell lymphopenia, but with impaired lymphocyte signaling through NF-κB, failure to generate memory and regulatory T cells, and hypogammaglobulinemia." (PMID 25627829, 2015). "The PIDs included the following: common variable immunodeficiency, severe combined immunodeficiency, DOCK8 deficiency, ataxia telangiectasia, CARD11 deficiency, MALT1 deficiency, chronic granulomatous disease, and a combined cellular and humoral immunodeficiency syndrome of unknown etiology." (PMID 36950172, 2023).
glioma (8 papers, 2018 to 2025). A benign or malignant brain and spinal cord tumor that arises from glial cells (astrocytes, oligodendrocytes, ependymal cells). "The mucosal-associated lymphoid tissue gene (MALT1), a negative regulator of Regnase-1 and other RNA binding proteins, was shown to regulate glioma cell survival." (PMID 38234734, 2023). "In this study, we investigated the role of mucosa‐associated lymphoma antigen 1 (MALT1) in glioma progression and evaluated the anti‐tumour activity and effectiveness of MI‐2, a MALT1 inhibitor in a pre‐clinical GBM model." (PMID 32452133, 2020). "However, the inhibitory effects of MI‐2 on the growth of glioma cells were reduced in the MALT1‐deficient cells." (PMID 32452133, 2020). "Notably, in glioma, the MALT1 protease enhances the immunosuppressive phenotype of TAMs through NF-κB pathway activation, while MALT1 inhibitors reverse this effect and restore antitumor immune responses." (PMID 41459510, 2025). "Therefore, whether MALT1 is also involved in regulating non‐canonical NF‐κB signalling or other signalling pathways in glioma cells should be confirmed in future studies." (PMID 32452133, 2020). "The five glioma subpopulations were as follows: C0 CHCHD2P9+ glioma cells (2,821 cells), C1 MALT1+ glioma cells (2,124 cells), C2 MT1G+ glioma cells (1,614 cells), C3 SOX4+ glioma cells (1,575 cells), and C4 ISG15+ glioma cells (128 cells)." (PMID 40630954, 2025). "Our study showed that silencing lncRNA HOXD-AS2 significantly inhibits the cell proliferation and tumorigenesis of glioma cells, and HOXD-AS2 can regulate the expression of MALT1 by serving as a molecular sponge of miR-3681-5p." (PMID 34802389, 2021).
multiple sclerosis (8 papers, 2014 to 2025). A progressive autoimmune disorder affecting the central nervous system resulting in demyelination. "MALT1 paracaspase inhibitors are currently under intense study as potential therapeutics against lymphomas, multiple sclerosis, colitis, and psoriatic skin diseases." (PMID 34721419, 2021). "Loss of MALT1 has formerly been shown to also interfere with T cell infiltration and expression of IL-17 in experimental autoimmune encephalitis (EAE) in mice, a well-known model of multiple sclerosis." (PMID 29367251, 2018). "The present study aimed to elucidate whether MALT1 protease inhibitors are also useful in the treatment of lymphocyte-mediated autoimmune pathologies such as multiple sclerosis (MS)." (PMID 25043939, 2014).
prostate carcinoma (8 papers, 2017 to 2023). A carcinoma that arises from epithelial cells of the prostate gland. "MALT1 (Mucosa-associated lymphoid tissue lymphoma translocation protein 1) had been identified as a key protein in the pathogenesis of different hematological and solid tumors, such as lung or prostate cancers." (PMID 36745330, 2023). "ARv7 enhances the MALT1/NF-κB-signaling pathway in an androgen-independent way to motivate cell proliferation, invasion, and tumor growth in human androgen-independent prostate cancer cells in vitro and in vivo." (PMID 37047218, 2023). "The results from this study indicate that androgen-stimulated MALT1 activates NF-κB signaling in the ARFL-positive prostate cancer cell lines, LNCaP and 22Rv1." (PMID 37047218, 2023). "To determine the role of the androgen analog, R1881, on the expression of MALT1 in AR-positive prostate cancer cells, we treated two ARFL-positive prostate cancer cells, LNCaP and 22Rv1, with various concentrations of R1881 for 24 h." (PMID 37047218, 2023). "Accordingly, our study suggested that a putative R1881/AR/MALT1/NF-κB-signaling pathway is involved in the regulation of PSA expression in ARFL-positive prostate cancer cells." (PMID 37047218, 2023). "MALT1 has been defined recently as an oncogene in human prostate cancer cells which enhances cell invasion and cell growth in vitro and in vivo." (PMID 37047218, 2023). "Overall, these results demonstrated that R1881 activates NF-κB signaling via MALT1 in prostate cancer cells." (PMID 37047218, 2023). "Our recent study verified that MALT1 is an NF-κB-upregulated oncogene, and a positive feedback loop was found in prostate carcinoma cells." (PMID 35053438, 2022). "Our recent study further revealed that MALT1 activates the IKK complex to induce nuclear NF-κB accumulation in prostate carcinoma cells." (PMID 35053438, 2022). "We investigated the functions and regulatory mechanisms of CAPE in relation to MALT1 in prostate carcinoma cells." (PMID 35053438, 2022). "MALT1 enhanced NF-κB activity in prostate carcinoma cells; moreover, NF-κB induced MALT1 expression determined by reporter and immunoblot assays, implying there is a positive feedback loop between MALT1 and NF-κB." (PMID 33802402, 2021). "The aims of this study are to determine the expressions of MALT1 in both prostate carcinoma cells and prostate tissues, and to examine the potential functions and regulatory mechanisms of MALT1 in prostate carcinoma cells." (PMID 33802402, 2021). "Taken together, these results indicate that MALT1 is an oncogene in prostate cancer in vitro and in vivo." (PMID 33802402, 2021). "We established xenograft models to investigate the tumorigenic potential of MALT1 in prostate cancer; 10 male nude mice were subcutaneously inoculated with LNCaP cells expressing shCtrl (NC group) or shMALT1 (KD group), with 5 mice in each group." (PMID 34926571, 2021).
prostate carcinoma (continued). "Overexpression or knockdown of MALT1 in prostate cancer PC-3 cells affected the oncogenic role of MALT1 in cell proliferation, migration, and invasion via the NF-κB pathway in vitro." (PMID 33802402, 2021). "This study investigated the functions and the potential regulatory mechanisms of MALT1 in the human prostate cancer cells." (PMID 33802402, 2021). "The results of RT-qPCR assays further indicated that MALT1 ubiquitously expressed in the prostate cancer cells." (PMID 33802402, 2021). "The induction of the transcriptional activation of endogenous MALT1 in DU145 cells by CRISPR/dCas9 lentiviral activation particles were used to confirm the biological functions of MALT1 in the prostate carcinoma cells." (PMID 33802402, 2021). "The present study demonstrated that MALT1 is one of the key proteins modulating NF-κB signaling in prostate carcinoma cells." (PMID 33802402, 2021). "However, the molecular mechanisms of the regulation of AR on MALT1 in androgen-dependent and -independent prostate cancer cells have yet to be clearly established." (PMID 37047218, 2023). "Next, we investigated whether androgen-induced MALT1 expression facilitates the nuclear translocation of NF-κB signaling in AR-positive prostate cancer cells." (PMID 37047218, 2023). "Meanwhile, a recent study revealed that the induction of the phosphorylation of IKKα by the ectopic overexpression of MALT1 facilitated the NF-κB subunits’ (p50 and p65) nuclear translocation to promote prostate cancer cell proliferation, invasion, and tumor growth in vitro and in vivo." (PMID 37047218, 2023). "Moreover, CAPE attenuated androgen-induced PSA and MALT1 expressions in AR-positive prostate carcinoma cells (LNCaP and 22Rv1)." (PMID 35053438, 2022). "We investigated the effect of CAPE on MALT1 expression in prostate carcinoma cells." (PMID 35053438, 2022). "In conclusion, MALT1 is a NF-κB-induced oncogene in the human prostate carcinoma cells." (PMID 33802402, 2021). "Furthermore, knockdown of MALT1 downregulated NF-κB activity in PC-3 cells, confirming the modulation of MALT1 on NF-κB signaling in prostate carcinoma cells." (PMID 33802402, 2021). "However, the role of MALT1 across cancers, especially in prostate cancer is still poorly understood." (PMID 34926571, 2021). "The activation of MALT1 on the expressions and secretions of IL-6 and CXCL5 was blocked under the treatment of MI-2 or CAPE, suggesting that upregulation of MALT1 on the IL-6 and CXCL5 expressions may rely on the MALT1/NF-κB pathway in prostate carcinoma cells." (PMID 33802402, 2021). "Taken together, MALT1 induced p65 translocation into the nucleus suggesting that MALT1 may be implied as an important tumor marker for prostate since studies confirmed that nuclear localization of NF-κB p65 as a prognostic biomarker in prostate cancer patients." (PMID 33802402, 2021). "This study confirmed the potential linkages between androgen and NF-κB activation by inducing MALT1 in the androgen receptor-full length (ARFL)-positive LNCaP and 22Rv1 prostate cancer cells." (PMID 37047218, 2023).
prostate carcinoma (continued). "Collectively, our results illustrate that MALT1 modulates the expressions of IL-6 and CXCL5 via NF-κB activation, thereby contributing to tumor progression and malignancy in prostate carcinoma cells." (PMID 33802402, 2021). "Since the nuclear translocation of p50 and p65 was facilitated by ARv7 to motivate NF-κB activity, the expressions of MALT1, prostate-specific antigen (PSA), and N-myc downstream regulated 1 (NDRG1) were therefore induced in ectopic ARv7-overexpressed prostate cancer cells." (PMID 37047218, 2023). "The RT-qPCR assays in this study showed that MALT1 exists in either metastatic or non-metastatic prostate cancer cells." (PMID 33802402, 2021). "MALT1 facilitated NF-κB subunits (p50 and p65) nuclear translocation to induce gene expression of interleukin 6 (IL-6) and C-X-C motif chemokine 5 (CXCL5) in prostate carcinoma cells." (PMID 33802402, 2021). "The metastatic prostate carcinoma cells (LNCaP, PC-3, and DU145) exhibited higher MALT1 protein and mRNA levels than non-metastatic cells (PZ-HPV-7 and CA-HPV-10), indicating that MALT1 expression in prostate carcinoma cells contributes to the malignancy in vitro." (PMID 33802402, 2021). "Interestingly, CAPE downregulated MALT1 expression in PC-3 cells, and this downregulation was also not blocked by any of the corresponding inhibitors; thus, CAPE may not affect MALT1 expression via the MAPK and AMPK signaling pathways in prostate carcinoma cells." (PMID 35053438, 2022).
fungal infections (7 papers, 2011 to 2024). "MALT1 deficiency is a congenital immunodeficiency characterized by recurrent bacterial, viral, and fungal infections." (PMID 36817458, 2023). "The obvious risk related to MALT1 inhibition is thus susceptibility to infections, particularly to fungal infections due to the link between dectin, MALT1, IL-1β and IL-17." (PMID 32870913, 2020). "Since Candida albicans infections are amongst the most common causes of invasive fungal infections in immunocompromised patients, we used two different C. albicans strains to investigate the importance of Malt1 signaling in anti-fungal immune responses." (PMID 21283787, 2011). "However, this patient did not carry any variants in CARD9, IL17RA, L17RC, IL17F, STAT1, DOCK8, MALT1, or TRAF3IP2 genes that can explain the susceptibility to a severe and invasive fungal infection." (PMID 35091979, 2022). "Thus, the marked impact of Malt1 inhibition on IL-1β and IL-23p19 expression in response to fungal infections translates to a block in TH-17 immunity." (PMID 21283787, 2011).
ulcerative colitis (7 papers, 2011 to 2024). An inflammatory bowel disease involving the mucosal surface of the large intestine and rectum. "Since cytokines play a critical role in ulcerative colitis, we examined the effect of MALT1 knockdown combined with MI-2 treatment on the expression of cytokines, including TNF-α and IL-17α, -22, and -1β, in intestinal tissue." (PMID 30249750, 2018). "For instance, MALT1 is upregulated in Crohn’s disease patients and ulcerative colitis patients compared to HCs, and it relates to elevated CRP, ESR, Crohn’s disease activity index score, or mayo score in the active patients." (PMID 35967391, 2022). "Our results indicate that inhibiting MALT1 is an effective treatment for severe ulcerative colitis." (PMID 30249750, 2018).
viral infections (7 papers, 2017 to 2023). "At the same time, however, our results indicate that MALT1 inhibitors can also increase the risk for severe virus infection in the brain or severe adverse effects upon vaccination with attenuated rabies viruses." (PMID 29367251, 2018). "Considering the potential risk in immune pathogenesis caused by excessive MALT1, nsp6-mediated MALT1 degradation may contribute to immune alleviation, which is a benefit for long-term virus infection." (PMID 35467421, 2022). "CARD9 is expressed in myeloid cells, MΦs, and DCs, and CARD9 complexes with BCL10 and MALT1 contribute to innate and adaptive immune responses to viral infections." (PMID 37334361, 2023). "Given that MALT1 positively regulates innate immunity and inflammation, the significance of MALT1 decrease is possibly to mollify inflammatory responses induced by viral infection." (PMID 35467421, 2022). "Here, we study the impact of MALT1 on virus infection in the brain, using the attenuated ERA rabies virus in different models of MALT1-deficient mice." (PMID 29367251, 2018). "Altogether, these data illustrate that MALT1 deficiency is associated with decreased infiltration and activation of inflammatory and immune cells in the brain upon ERA virus infection." (PMID 29367251, 2018). "Although MALT1 deficiency has been shown to protect against experimental autoimmune encephalomyelitis, nothing is known about the impact of MALT1 on virus infection in the central nervous system." (PMID 29367251, 2018). "Notably, antiviral and inflammatory gene expression is significantly disrupted in the brain of MALT1−/− mice at the pre-symptomatic phase of Evelyn–Rotnycki–Abelseth (ERA) virus infection, rendering it neurovirulent." (PMID 38140602, 2023). "The role of MALT1 in viral infection is, however, largely unknown." (PMID 29367251, 2018). "The MALT1 deficiency is associated with bronchiectasis, mastoiditis, chronic aphthous ulcers, gastritis, gingivitis, duodenitis and meningitis while the BCL10 PID is associated with hypogammaglobulinemia, gastroenteritis, otitis, respiratory tract infection and several viral infections." (PMID 28448599, 2017). "The NF-κB regulator MALT1 promotes canonical NF-κB expression, VSV replication in CD169+ cells, and immune activation during viral infection." (PMID 29142134, 2018). "MALT1 protein levels dramatically decreased at the late stage of PRRSV infection (especially after 36 hpi) with no strain specificity, and a high dose of viral infection (MOI of 10) induced more rapid decrease of MALT1." (PMID 35467421, 2022). "Finally, treatment of wild-type mice with mepazine, a MALT1 protease inhibitor, also led to mortality upon ERA virus infection." (PMID 29367251, 2018).